RN7SL225P (RNA, 7SL, cytoplasmic 225, pseudogene)
Gene: Miscellaneous RNA gene on chromosome 11 (86,324,012 to 86,324,309, reverse strand). Ensembl gene ENSG00000239856.
Homologues: Orthologues: chimpanzee Metazoa_SRP (99% identical), macaque Metazoa_SRP (93% identical), dog Metazoa_SRP (67% identical). Paralogues in human: RN7SL2 (78% identical), RN7SL1 (77% identical), RN7SL357P (77% identical), RN7SL543P (77% identical), RN7SL239P (76% identical), RN7SL3 (76% identical), RN7SL597P (76% identical), RN7SL361P (76% identical), RN7SL444P (76% identical), RN7SL566P (76% identical), RN7SL251P (75% identical), RN7SL646P (75% identical), and 704 more.